RNU7-144P (RNA, U7 small nuclear 144 pseudogene)
Gene: Small nuclear RNA gene on chromosome 20 (48,494,234 to 48,494,309, reverse strand). Ensembl gene ENSG00000238452.
Homologues: Orthologues: chimpanzee U7 (100% identical), dog U7 (63% identical). Paralogues in human: RNU7-173P (87% identical), RNU7-92P (87% identical), RNU7-104P (64% identical), RNU7-79P (64% identical), RNU7-80P (64% identical), RNU7-157P (63% identical), RNU7-43P (62% identical), RNU7-140P (61% identical), RNU7-65P (61% identical), RNU7-11P (59% identical), RNU7-13P (59% identical), RNU7-18P (59% identical), and 141 more.